IL2 (interleukin 2)
Diseases named in the same sentence as IL2 in open-access papers (continued):
Sharing a sentence is not in itself a finding about the gene and the disease.
hairy cell leukemia (13 papers, 2014 to 2025). Hairy cell leukemia (HCL) is a rare type of leukemia in which abnormal B-lymphocytes are present in the bone marrow, spleen and peripheral blood. "Since the first immunotherapy cytokine interferon-α (IFNα) was approved by the U.S. Food and Drug Administration (FDA) in 1986 for hairy cell leukemia, early-stage cancer immunotherapy from cytokines to interleukin-2 (IL-2) has shown limited therapeutic effect with high toxicity." (PMID 33918635, 2021). "IFNα was the first cytokine approved for human cancer treatment (hairy cell leukemia; HCL) followed by approval of high-dose IL-2 (HDIL-2) for metastatic renal cell carcinoma (mRCC) and metastatic melanoma (MM)." (PMID 37065938, 2023).
liver fibrosis (13 papers, 2014 to 2025). "An increased level of IL-2 is associated with hepatic fibrosis in humans with ALD." (PMID 31998436, 2020). "Compared to the untreated liver fibrosis group, the expression of inflammatory factors including IL-1, IL-2, IL-6, IL-8, IL-10, and TNF-α were significantly decreased in the hBM-MSCs and hBM-MSCs-Ex treatment groups (p < 0.05)." (PMID 30885249, 2019). "Consistently, aggravated liver fibrosis development in TcrbKO mice was confirmed by elevated fibrogenic gene expression (Sma, Col1, Tgfb), along with abnormal intrahepatic immune status (including alleviated levels of Il2, Il6, Il23, Ifng, and enhanced levels of Il17 and Tnfa)." (PMID 33391261, 2020). "Caspase-1 expression correlated with elastography-based liver fibrosis (r = 0.35, p = 0.02), whereas P2X7R, P2X4R, NRLP3, Caspase-1, and IL-2 expression correlated with circulating markers of disease severity." (PMID 35806450, 2022). "The Th-1 immunity profile (IL-2, IL-12, TNF-α, and IFN-γ) is correlated with liver fibrosis in patients with chronic hepatitis C, whereas Th2 immunity profile (IL-4 and IL-10) cannot control viral clearance." (PMID 27413763, 2016). "More sensitive cytokine-specific ELISA assays were performed to assess whether plasma concentrations of GM-CSF, IL-2 and/or VEGF could be considered as potential candidate biomarkers of schistosomiasis infection and/or liver fibrosis." (PMID 40092989, 2025). "The stage of liver fibrosis did not correlate with the serum markers of inflammatory reaction (hsCRP, IL2, IL6, p>0.05)." (PMID 25350286, 2014). "Moreover, oxidative stress can increase the levels of IL-2, TNF, and IL-2, which may contribute to hepatic fibrosis." (PMID 39555193, 2024). "Both baseline increased expression of IFNγ and IL2 and subsequent decrement after SVR were observed irrespective of HCV genotype or liver fibrosis measured by transient elastography." (PMID 33917265, 2021).
myocardial infarction (13 papers, 2014 to 2025). Gross necrosis of the myocardium, as a result of interruption of the blood supply to the area, as in coronary thrombosis. "Five SAEs occurred, four of which were unrelated to TIL/IL-2/anti-PD-1 therapy: myocardial infarction (MI) (only SAE considered treatment-related) - possibly linked to nivolumab (anti-PD-1) due to pre-existing cardiovascular risks." (PMID 41527622, 2025). "A final–and atypical–finding comes from patients with acute myocardial infarction in an Iranian hospital; among 4 cytokines measured in both the circulation and saliva, high inter-compartmental associations (all with p values of <0.001) were found for three: IL-2; IL-6; and TNF-α." (PMID 26075910, 2015). "In early studies, 1–6% of patients suffered a myocardial infarction following IL-2 therapy, but the incidence has since declined as a result of pre-therapy functional cardiac imaging, as was performed in all patients in the current study." (PMID 35741162, 2022). "Grade 4 treatment-related toxicity occurred in only one patient (3A) who developed myocardial infarction that was determined to be possibly related to IL-2." (PMID 24565030, 2014). "On the one hand, plasma levels of IL-2 were shown to be elevated in patients with acute myocardial infarction, angina pectoris, and dilated cardiomyopathy, while on the other hand, there are reports that suggest a potential therapeutic effect of IL-2 in the setting of acute myocardial infarction." (PMID 33195446, 2020). "IL‐2 was proven to protect cardiac function in mouse myocardial infarction models." (PMID 32406586, 2020). "Here, we investigate whether the IL-2 complex attenuates wound healing and structural remodeling after myocardial infarction by expanding Treg in murine models." (PMID 27144181, 2016). "Furthermore, in a mouse model of myocardial infarction, TNF-α mRNA, IL-1α, IL-2, IL-4, IL-5, IL-6, IL-10, IL-17A, TNF-α, IFN-γ, and GM-CSF expression were all lower in the infarct area of TLR4-deficient mice compared with wild-type mice." (PMID 30399158, 2018). "No patient developed a myocardial infarction following IL-2 therapy in this study." (PMID 35741162, 2022).
pulmonary disease (13 papers, 2006 to 2024). "Multifunctional CD4+ Th1 cells, co-expressing IFN-γ/TNF-α/IL-2 or IFN-γ/IL-2 or IFN-γ/TNF-α have been shown to be associated with protection against active pulmonary disease in TB." (PMID 25211342, 2014). "Though IL-2 plays a significant role in pulmonary diseases, it is unclear whether IL-2 is associated with CAP." (PMID 38967887, 2024). "IL-2 is a crucial cytokine for pulmonary diseases and is associated with COPD." (PMID 36836801, 2023). "We also assessed the association of cavitary lung disease and other measures of bacillary burden with IFN-γ, IL-2, and TNF responses in HHCs." (PMID 39606489, 2024). "The prior studies have shown that interleukin-2 (IL-2) exerts important roles in the pathological and physiological processes of lung diseases." (PMID 38967887, 2024). "Published research studies have shown that IL-2 is strongly connected to the biological processes of many lung diseases." (PMID 38967887, 2024). "The limited number of patients with these characteristics means that we cannot draw any firm conclusions concerning the usefulness of the combination of sorafenib and IL-2 in patients with only lung disease." (PMID 21448165, 2011). "In the presence of pulmonary metastases, locoregional administration of inhaled-IL-2 was reported to yield low toxicity combined with objective response rates of pulmonary disease of 2.5–21%." (PMID 16909131, 2006). "Recent surveys have identified the correlations between IL-2 and several pulmonary diseases." (PMID 38967887, 2024). "When assessing smoking related pulmonary disease, biomarkers of inflammation such as IL-2, IL-6, IL-8, and eotaxin may add additional modest predictive value on top of clinical variables alone." (PMID 29065892, 2017). "IL-2 (p=0.02) and IFN-γ (p=0.001), but not TNF (p=0.79), were positively associated with cavitary lung disease regardless of CAC status." (PMID 39606489, 2024). "While IL-2 complex treatment dramatically increases Th2 cell accumulation and enhances pulmonary disease, ILC numbers are not affected by IL-2 complex treatment in our model." (PMID 25764512, 2015). "IP-10, in contrast to IFN-γ, TNF-α, IL-2, IL-8, MIP-1α, MIP-1β and RANTES, is detectable in the urine of patients with pulmonary diseases in the absence of renal dysfunctions." (PMID 21092156, 2010). "For the first time, IP-10 (in contrast to IFN-γ, TNF-α, IL-2, IL-8, MIP-1α, MIP-1β and RANTES) has been detected in the urine of patients with lung disease in the absence of renal illnesses." (PMID 21092156, 2010).
Arrhythmia (12 papers, 2015 to 2024). Any cardiac rhythm other than the normal sinus rhythm. "Although the role of Scn3b in AIC has not been reported ever, the increased expression of Scn3b modulated by interleukin 2 was found to be associated with arrhythmia." (PMID 34732131, 2021). "Serum IL-2 levels are associated with multiple cardiovascular diseases such as coronary artery disease and cardiac arrhythmias (CAs)." (PMID 35083300, 2021). "Cardiac arrhythmias (CAs) are generally caused by disruption of the cardiac conduction system; interleukin-2 (IL-2) is a key player in the pathological process of CAs." (PMID 35083300, 2021). "IL-2 has been reported to be associated with various cardiac arrhythmias including atrial fibrillation (AF) and ventricular tachycardia (VT)." (PMID 26728597, 2016). "Although studies observed that IL-2 was associated with the morbidity of arrhythmias, however, how IL-2 affects the cardiac electrophysiology is still unknown." (PMID 26728597, 2016). "IL-2 is a pro-inflammatory factor which is associated with the morbidity of arrhythmias, however, how IL-2 affects the cardiac electrophysiology is still unknown." (PMID 26728597, 2016). "Arrhythmias may be caused not only by anthracyclines use but also by cisplatin, taxanes, vinca alkaloids, platinum, arsenic, thalidomide, antimetabolites, and interleukin-2 (IL-2)." (PMID 32466499, 2020). "It remains to be elucidated if higher incidence of arrhythmia is a dose-dependent phenomenon with use of IL-2 therapy similar to therapy with anthracyclines." (PMID 29399586, 2018). "The finding that IL-2 therapy acutely induces relative QT interval prolongation may be a potential mechanism for the arrhythmias that have previously been reported following IL-2 therapy." (PMID 35741162, 2022). "In conclusion, the present study suggested that IL-2, a pro-inflammatory cytokine, may play role in the arrhythmia by its affection on SCN3B and sodium current density." (PMID 26728597, 2016). "In present study, we observed that high expression level of the SCN3B which induced by IL-2 can increase the sodium current density, these results suggested that increased serum level of IL-2 can affect various cardiac arrhythmias by its effect on the SCN3B and sodium current density." (PMID 26728597, 2016). "IL-2 is a potent inducer for T cell proliferation as well as Th1 and Th2 differentiation and has been demonstrated may act as a key factor for many cardiovascular diseases and arrhythmia such as AF." (PMID 26728597, 2016).
epilepsy (12 papers, 2012 to 2025). A brain disorder characterized by episodes of abnormally increased neuronal discharge resulting in transient episodes of sensory or motor neurological dysfunction, or psychic dysfunction. "On the other hand, we have found that IL-2 increases the risk of epilepsy." (PMID 38855442, 2024). "The “Epilepsy-only” patients had significantly higher serum and mRNA levels of IL-1α, β, IL-2,6,8, and TNF-α compared to the controls and the “Cannabis+Epilepsy” group (p = 0.0001)." (PMID 31757102, 2019). "Intraventricular administration of IL-2 in DBA/2 mice promotes seizure generation in various models of experimental epilepsy." (PMID 29017522, 2017). "For epilepsy and bipolar disorder, overlapping results regarding the cytokine system have been reported, namely, alterations of IL-1β, IL-2, IL-4, IL-6, and TNF-α." (PMID 24757498, 2014). "In epilepsy patient plasmas, we found that concentrations of anti-inflammatory sICAM5 are reduced (p = 0.002) and pro-inflammatory IL-1β, IL-2, and IL-8 are elevated." (PMID 23293627, 2012). "The higher plasma levels observed in this study of IL-6, IL-1β, IL-2, and IL-8, also support the concept that innate immunity is chronically activated in epilepsy." (PMID 23293627, 2012). "We have observed a decreased level of IL-2 in blood plasma in epilepsy." (PMID 36293411, 2022). "Cytokine and chemokine profiles in children with FIRES show an elevation of Th1 specific cytokines (IL-2, TNF, INF-γ) and chemokines when compared to children with other forms of epilepsy or encephalopathy." (PMID 40310164, 2025). "Compared with CBZ use, VPA use led to lower levels of IL-2, IL-8, and TNF-α in 120 epilepsy patients, including 60 VPA- and 60 CBZ-treated patients, which is similar to our findings." (PMID 40806813, 2025). "The serum and gene expression of the inflammatory cytokines—IL-1α, IL-1β, IL-2, IL-6, IL-8 and TNF-α—showed the highest levels among the “Epilepsy-only” group followed by lower levels in the epilepsy–cannabis users and finally the lowest levels in the healthy controls." (PMID 31757102, 2019). "Interestingly, IL-2 and IL-10 had high variability across all tissues independent of epilepsy status, whereas VEGF, IL-6, and IL-8 showed greater variability in epileptic compared to nonepileptic tissues." (PMID 27737716, 2016).
hemophagocytic lymphohistiocytosis (12 papers, 2016 to 2025). "Tocilizumab is able to attenuate the levels of IFN‐γ, IL10, and IL2, and treat refractory hemophagocytic lymphohistiocytosis (HLH) with expansion of cytotoxic T and NK cells." (PMID 37193304, 2023). "SARS-CoV-2 increases interferon gamma, tumor necrosis factor-α, macrophage inflammatory protein-1 alpha, IL-2, IL-6, IL-7, IL-10, in patients, that show a form of secondary hemophagocytic lymphohistiocytosis or macrophage activation syndrome (sHLH/MAS)." (PMID 33494816, 2021). "HLH: hemophagocytic lymphohistiocytosis; NK: natural killer; IL-2: interleukin-2." (PMID 37065291, 2023). "The cytokine storm of IL-2, IL-6, TNF-α, and IFN-γ observed in both forms of hemophagocytic lymphohistiocytosis (HLH) induces a hyperactivated state of both macrophages and cytotoxic T cells." (PMID 39318634, 2024).
hypothyroidism (12 papers, 2010 to 2025). Abnormally low levels of thyroid hormone. "TSH, TPOAb, CRP, percentage of Th17 cells, Th17/Treg ratio, IL-2, IL-6, IL-10 and TNFα levels increased significantly in the hypothyroidism group compared to the control group, and FT4 levels and percentage of Treg cells decreased significantly." (PMID 41573549, 2025). "Serum levels of TNF-α and interleukin-2 (IL-2) were found to be considerably greater in pregnant women with hypothyroidism than in normal healthy women." (PMID 40237055, 2025). "The hypothyroidism group had higher serum IL-2, TNF-α, and IFN-γ levels, and lower IL-10 levels, than the control group." (PMID 37051293, 2023). "Alternative explanations include the direct effects of cytokines on thyroid function; e.g., interferon alpha and IL-2 were demonstrated to elicit hypothyroidism." (PMID 38068542, 2023). "were significantly higher than group B. Abnormal Th17 regulation mediated by IL-2 and low TGF-b concentrations is associated with hypothyroidism in chronically-infected HCV patients." (PMID 21188205, 2010). "We found that CRP, IL-2, IL-6 and TNF-α levels were increased in pregnant women with hypothyroidism in the first half of pregnancy." (PMID 41573549, 2025). "Hypothyroidism patients had increased C-reactive protein (CRP), interleukin-2 (IL-2), IL-4, IL-10, and tumor necrosis factor (TNF)-α levels." (PMID 39185088, 2024). "We found that the CRP, IL-2, IL-4, IL-10, and TNF-α levels were greater in the hypothyroidism group than in the control group." (PMID 39185088, 2024). "The serum CRP, IL-2, IL-4, IL-10 and TNF-α levels in the hypothyroidism group were greater than those in the control group (P < 0.05)." (PMID 39185088, 2024). "The serum levels of IL-2, TNF-α, and IFN-γ in the hypothyroidism group were significantly increased (p < 0.01, p < 0.001, p < 0.001, respectively), whereas the level of IL-10 was dramatically reduced (p < 0.001), compared to those in the control group." (PMID 37051293, 2023). "In the present study, serum IL-2, TNF-α, and IFN-γ levels were significantly increased in the hypothyroidism group compared to those in the control group." (PMID 37051293, 2023). "Additionally, hs-CRP, IL-2, IL-6 and TNF-α levels were elevated in the hypothyroidism group, suggesting an inflammatory response in these patients during the first half of pregnancy, aligning with previous studies." (PMID 40443669, 2025). "This suggests that hypothyroidism was not related to interleukin-2 despite the fact that transgenic mice with IL-12 serum concentrations in the 150 pg/ml range develop a moderate primary hypothyroidism." (PMID 21188205, 2010).
ischemic stroke (12 papers, 2019 to 2026). A stroke disorder caused by obstruction of blood flow to the brain, due to thrombotic (local blood clot formation) or embolic (due to a blood clot or other material traveling from another site) event. "The present study also revealed insights into the initial inflammatory response to ischaemic stroke within 24 h and recognised the potential pathogenic function of IL-2/IL-2R autocrine loops in T lymphocyte differentiation after AIS." (PMID 32795376, 2020). "Interleukins such as TNF-α, IL-2, IL-4, IL-6 and IL-10, secreted by lymphocytes, play an important role in the pathogenesis and prognosis of ischemic stroke." (PMID 39204113, 2024). "has found that ischemic stroke patients with poor functional outcomes at 3 months have significantly higher levels of IL-2 receptor α (sIL-2Rα) and lower levels of IL-2 than patients with good outcomes." (PMID 35173738, 2022). "IL-2/IL-2R treatment also decreased infiltration of inflammatory cells while also inhibiting the increase of inflammatory cytokines following an ischemic stroke." (PMID 33830475, 2021). "Accordingly, inhibition or genetic knockdown of the channel has been reported to reduce IL-2 production by T cells and IL-β1 and TNFα levels by microglia in ischemic stroke." (PMID 32150577, 2020). "IL-2/IL-2Ab promotes the expression of CD39 and CD73 in expanded Tregs, the deficiency of which may reduce the protective action of Tregs stimulated by IL-2/IL-2Ab in ischemic stroke mice." (PMID 35173738, 2022). "IL-2 also reduces demyelination after ischemic stroke by suppressing CD8+ T cells." (PMID 36080256, 2022). "The IL-2/IL-2 antibody complex (IL-2/IL-2Ab) may improve the prognosis of ischemic stroke by regulating the amount of regulatory T cells (Tregs) in the body." (PMID 35173738, 2022). "In addition, pre- or post-treatment of an IL-2/IL-2-antibody complex succeeded in reducing the infarct volume and improving neurological functions on 3 days after ischemic stroke in a Treg-dependent manner." (PMID 34335623, 2021). "Therefore, promoting Treg activity via the IL-2/IL-2R adjunctive treatment may substantially alleviate the severe inflammatory conditions that proceeds after ischemic stroke." (PMID 33830475, 2021).
leprosy (12 papers, 2012 to 2025). Leprosy is a chronic infectious disease affecting primarily the skin and peripheral nervous system. "NK cells are also recruited to leprosy lesions by IL-2, where they can clear and eliminate infected macrophages and Schwann cells." (PMID 36901962, 2023). "The interleukin-2 concentration increased 2 weeks after vaccination compared to pre-vaccination in leprosy cured group, but declined in control group (0.92 pg/ml vs −0.02 pg/ml, P = .0147)." (PMID 34397815, 2021). "IL-2 considered to be critical for both types of Treg cells, showed decreased expression in both types of leprosy as compared to healthy subjects in PBMC and between the two leprosy types in the skin." (PMID 24454972, 2014). "While Tuberculoid (TT) or Paucibacillary (PB) leprosy patients show a Th1 immune profile with higher levels of interleukin-2 (IL-2) and interferon-γ (IFN-γ), lepromatous (LL) or multibacillary (MB) patients exhibit a Th2 immune profile with the rise in IL-10 and IL-4 interleukins." (PMID 40636115, 2025). "Early studies of leprosy intradermal cytokine expression determined that leprosy polarity is associated with TH2 cytokines IL4, IL5, IL10 in lepromatous lesions, and TH1 polar cytokines, IFNG, IL2, in tuberculoid lesions." (PMID 25412496, 2014). "Additionally, we observed that a classification of leprosy patients is possible using transcriptomics since a set of genes were increased in BL/LL patients (CD46, CXCL10, FCGR1A, HDAC2 and TLR4) and TT/BT showed a higher expression of IL2 and TLR6." (PMID 31784594, 2019). "As expected, IL-2 expression was decreased in lepromatous as compared to tuberculoid (p<0.006) and normal skin (p<0.03) but was not discriminatory in antigen stimulated PBMC of leprosy types." (PMID 24454972, 2014).